RAC1 (Rac family small GTPase 1)
Diseases named in the same sentence as RAC1 in open-access papers (continued):
Sharing a sentence is not in itself a finding about the gene and the disease.
melanoma (continued). "Another study pointing to the importance of WAVE2 as a RAC1 effector, described how in mouse melanoma cells with ectopic overexpression of constitutive active RAC1, there was an increase in invasiveness that was reverted by WAVE2 RNAi." (PMID 34827551, 2021). "RAC1 is one of the best characterized Rho GTPases that regulate crucial processes for melanoma tumorigenesis and metastasis." (PMID 34827551, 2021). "We found that the nevogenic melanomas were associated with mutations in BRAF, while the CSD melanomas were associated with mutations in NF1, ROS1, GNA11, and RAC1." (PMID 34680367, 2021). "The CSD melanomas, in contrast, showed mutations in a diverse group of genes that included NF1, ROS1, GNA11, and RAC1." (PMID 34680367, 2021). "Immunohistochemistry showed that Cdc42, Rac1, and RhoA were constitutively expressed in the nuclei of melanoma cells of the untreated group, and NX-5 treatment decreased their expression." (PMID 34201921, 2021). "The Rac1 mutant (P29s) melanoma cells can up-regulate the formation of platelet lipoprotein through dendritic actin polymerization." (PMID 34079763, 2021). "Overexpression of RAC1 in melanoma cells increased ROS levels that inhibited PP2A preventing thereby dephosphorylation of Bcl-2." (PMID 34827551, 2021). "Cullin3, via the adaptor protein KCTD5, also regulates cell adhesion and spreading in murine melanoma cells, suggestive of Rac1 activation." (PMID 34136490, 2021). "In melanocytes, Rac1 with Rac1 P29S cooperates with oncogenic B-Raf and Nf1 to promote melanoma development and resistance to therapy." (PMID 34071831, 2021). "A recurrent activating mutation in RAC1, a RAS-related member of the Rho GTPases subfamily, has been identified in 9.2% of sun-exposed melanomas." (PMID 34123788, 2021). "Using the 3D melanoma model prepared in this way, the reduction in the expression of Rho-family GTPase (Cdc42/Rac1/RhoA) protein by NX-5 treatment was confirmed by immunohistochemical staining." (PMID 34201921, 2021). "Oncogenes linked to melanoma progression were also amplified, including NRAS, KIT and RAC1, the latter highly amplified in four patients in regions with LOH at copy numbers of 5 (patient ETH-F), 6 (patients CAS-E and SK-H) and 7 (patient CAS-F)." (PMID 33664264, 2021). "One of the possible signaling pathways of RAC1 in the promotion of melanoma is through its binding to Bcl-2." (PMID 34827551, 2021). "In melanoma, UNR is usually highly expressed in melanoma and associated with invasion and metastasis by activating the extension of VIM and RAC1 mRNA." (PMID 32653017, 2020). "Similar to ropivacaine, we found that lidocaine also significantly decreased the activities of RhoA, Rac1 and Ras in melanoma cells." (PMID 32085741, 2020). "To do this, we employed a B16-F1 melanoma clone that had arisen from our attempts to disrupt Rac1/2/3 genes in the CYFIP1/2 null background." (PMID 32486060, 2020). "Melanoma patients with Rac1P29S somatic mutation are resistant to RAF inhibitors such as vemurafenib and dabrafenib, whereas silencing of Rac1 in these cells reversed this resistant phenotype 24." (PMID 32057095, 2020). "ShcD overexpression sustains amoeboid movement in melanoma cells, by suppressing the Rac1 signaling pathway through the confinement of DOCK4 in the cytoplasm." (PMID 33202906, 2020). "Accordingly, an increased PD-L1 expression was found in patients with RAC1P29S mutant melanomas, compared with wild-type RAC1 melanoma patients." (PMID 33072757, 2020). "Here, we provide novel data demonstrating that KCTD5 regulates cell migration, spreading, focal adhesion dynamics, Rac1 activity and intracellular Ca2+ levels of melanoma cells." (PMID 33053687, 2020). "Together, our data indicate that KCTD5 is a negative regulator for the migration of melanoma cells by affecting two crucial molecular players of this process: Rac1 activity and Ca2+ signaling." (PMID 33053687, 2020).
melanoma (continued). "The treatment of ShcD-knockdown cells with the selective Rac1 inhibitor NSC23766, as well as the silencing of Rac1, rescued the rounded phenotype of melanoma cells, indicating that ShcD actively inhibits Rac1, inducing the rounded morphology of melanoma cells." (PMID 33202906, 2020). "Overexpression of PAK is a known driver of MAPKi resistance, and constitutive activating mutations of RAC1 (RAC1P29S), an upstream effector of PAK1, are found in 10% of MAPKi progression melanoma tumors." (PMID 32346533, 2020). "For example, substitution of proline 29 to serine (P29S) in Rac1 was observed in 4% to 9% of sun-exposed melanomas." (PMID 32392742, 2020). "We found that ropivacaine significantly decreased RhoA, Rac1 as well as Ras activities in melanoma cells." (PMID 32085741, 2020). "Our findings suggest that the critical RAC1 effector in melanoma is the transcription factor complex SRF/MRTF, which initiates a switch to a mesenchymal-like state characterized by therapy resistance." (PMID 31257073, 2019). "Using the Skin Cutaneous Melanoma (SKCM) database in the TCGA, they also demonstrated that PD-L1 expression was significantly increased in conditions of RAC1 P29S compared to RAC1 WT in melanoma patients." (PMID 31027363, 2019). "Although we observed an increase in Rac1 activity in BRAFi‐R melanoma cells, we did not observe a statistically significant reduction in the elevated Rac1 activity of BRAFi‐R melanoma cells after combined treatment with an IL‐6 Ab and Box5." (PMID 30582770, 2019). "Overall, there is a considerable body of evidence pointing to an important role for RAC1 signaling in melanoma, but the nature of its function remains largely unclear." (PMID 31257073, 2019). "Bladder/urinary tract cancers, lung cancers, and melanoma are the cancers among which a higher frequency of alterations of the RAC1 gene has been identified, in contrast to other solid tumors like breast, colorectal, and endometrial cancers." (PMID 31027363, 2019). "The consensus from published studies is that targeting PAK proteins provides the best potential treatment for RAC1 mutant melanomas." (PMID 31027363, 2019). "Genetic deletion or pharmacological inhibition of RAC1 in NRAS Q61K-induced melanoma has been shown to suppresses tumor growth, lymph node spread, and tumor cell invasiveness, suggesting a potential value for RAC1 inhibition in this type of tumors." (PMID 31027363, 2019). "In melanoma, lung, and uterine cancers, although the percentage of total alteration of the RAC1 gene is around 5–7%, the type of alteration varied depending on the organ-type." (PMID 31027363, 2019). "First, RAC1 was knocked down to determine its contribution to the survival of RAC1P29S human melanoma cells." (PMID 31257073, 2019). "We interrogated which downstream effectors are used by RAC1P29S for the promotion of survival in the hope of uncovering therapeutic targets for P29S mutant RAC1-driven melanoma." (PMID 31257073, 2019). "Recently, a recurrent somatic missense mutation at codon 29 of RAC1 in the highly conserved switch I domain that results in the substitution of proline to a serine residue (RAC1 P29S) was discovered in up to 9% of sun-exposed melanomas." (PMID 31027363, 2019). "For example, patient MM475 had multiple recognized melanoma driver mutations including BRAF p.V600R, RAC1 p.P29S, MAP2K1 p.P124S, TERT C228T, and DPH3 C8T." (PMID 30312528, 2019). "Activation of Rab5 in turn increases the activity of Rac1 to enhance migration and invasion of breast and colon cancer cells, as well as melanoma cells." (PMID 31362353, 2019). "After B-RAF V600 and N-RAS Q61, RAC1 P29S is the most frequent mutation found in wild-type for BRAF and N-RAS melanomas and is detected in 5–9% of all melanomas." (PMID 31248017, 2019).
melanoma (continued). "Our results highlighted the importance of RAC1 enzyme and cellular oxidation-metabolizing efficiency controlled by SOD2 in association with ROS-mediated risk of melanoma." (PMID 29342889, 2018). "RAC1 been previously reported in SKCM and other datasets and was associated with melanoma progression, suppression of host immune response, and drug resistance." (PMID 30662871, 2018). "Another study showed that Rac1/P29S expression inhibited invadopodia formation in melanoma cell lines." (PMID 30544828, 2018). "Since the identification of Rac1/P29S in melanomas, there have been additional reports of Rac1 and Rac2 mutants, as identified in public databases and in common cell lines." (PMID 30544828, 2018). "The expression levels of the identified target genes encoding CTGF, THBS1, STMN1, BCL9, RAC1 and MCL1 allowed discrimination between phenotypic groups of melanoma cell lines with high or low-invasive capacity, respectively." (PMID 30197759, 2018). "A recent study has shown that high expression of RAC1 protein in primary cutaneous melanoma samples was associated with thinner melanomas, BRAFV600 mutation and with RAC1 mutation." (PMID 30662871, 2018). "Although Rac1 can promote the formation of stress fibers and adhesion plaque, Rac1 overexpression can inhibit the migration and invasion of melanoma cells." (PMID 28404912, 2017). "In B16-F10 melanoma cells, both Rac1 transfection and CT04 treatment reduced the percentages of cells in early and late apoptosis to 2.8% and 3.8%, for Rac1-transfected cells, and to 4.3% and 2.9%, for CT04-treated cells, respectively." (PMID 28915620, 2017). "RAC1, encoding a RAS-related member of the Rho superfamily of GTPases, was mutated in 5% of melanomas." (PMID 29156643, 2017). "We utilized a Cdc42-PAK functional assay to better evaluate the activation of this family of GTPases in melanoma and determined that RhoJ, Cdc42, and Rac1/2/3 interact with PAK in melanoma cells when they are GTP-bound but not when they are loaded with GDP." (PMID 28753606, 2017). "A further clinical study suggested the potential of Rac1 P29S as a predictive biomarker for resistance to therapy in melanoma patients under treatment with these inhibitors." (PMID 27104658, 2016). "Next, we showed that melanoma cells in the presence of hydrogen peroxide had lower actomyosin levels and higher RAC1 activity, which resulted in reduced invasiveness through a 3D matrix." (PMID 27308633, 2016). "According to the most recent literature, P29 results altered in approximately 3.9 % of TCGA skin cutaneous melanoma patients suggesting that RAC1 is a melanoma oncogene." (PMID 26860319, 2016). "Recently, genetic subsets of melanoma have been characterized, especially with known driver mutations such as BRAF, NRAS, GNAQ, RAC1, C-KIT, and others." (PMID 26871475, 2016). "In fact, the expression of RAC1 P29S in sensitive BRAF-mutant melanoma cell lines confers resistance to treatment with RAF inhibitors." (PMID 26860319, 2016). "Mechanistically, we find that MT1-MMP downregulates SPRY4 expression trough an MMP2/RAC1 axis we previously showed promotes melanoma cell motility downstream of MT1-MMP." (PMID 26392417, 2015). "We have previously shown that MT1-MMP mediated melanoma cell migration depends on the activation of an MMP2/RAC1 signaling axis." (PMID 26392417, 2015). "Overexpression or knockdown of Swiprosin-1 modulated migration and invasion of B16F10 melanoma cells through Rac1 and RhoA signaling pathways." (PMID 26079945, 2015). "SPARC can regulate melanoma cell transition to an aggressive mesenchymal phenotype (that implies Rac1-GDP localization at the cytoplasm) by inducing the shift from E- to N-cadherin expression." (PMID 26248315, 2015). "The dominant negative mutant of Rac1 (Rac1N17) attenuates paclitaxel-evoked apoptosis in melanoma M14 cells through upregulation of Hsp27, which inhibits the downstream drug-elicited caspase-3 activation." (PMID 24586549, 2014).
melanoma (continued). "As expected, this list included well documented frequent oncogenic drivers of melanoma, including hotspot mutations in BRAF, NRAS, RAC1, PPP6C, TRRAP, MAP3K5 and BCL2L12." (PMID 24913145, 2014). "Third, our mutation network shows the interactions and context of mutation genes, providing an interpretation to facilitate biological functional analysis in the future, such as further investigation of the novel gene RAC1 in melanoma." (PMID 24516372, 2014). "The role of Rac1 and RhoA in dendrite formation by human melanocytes and melanoma cells was defined by several studies." (PMID 24649261, 2013). "In summary, our results suggest that narrow-band UVB radiation specifically activates the Rac1 signaling pathway, leading to F-actin rearrangement and resulting in increased dendrite formation in B16 melanoma cells." (PMID 24649261, 2013). "Overexpression of the constitutive active form of MKK6 resulted in significant elongation of the dendrites via the upregulation of Cdc42 and Rac1 expression in the SK-mel-24 human melanoma cell line." (PMID 24649261, 2013). "The effect of small GTPases, such as Rac1 and RhoA, on the morphology of B16 melanoma cells treated with narrow-band UVB radiation was investigated." (PMID 24649261, 2013). "Noteworthy, PPP6C mutations were more frequent in melanomas that were mutated for both BRAF and NRAS, while RAC1 mutations were more frequent in melanomas that were wild-type for both BRAF and NRAS." (PMID 24416617, 2013). "Treatment of B16 melanoma cells with narrow-band UVB radiation resulted in the activation of Rac1 in a time-dependent manner." (PMID 24649261, 2013). "Here we show that Ras and Rac1, oncogenes that driver deregulated process such as proliferation and apoptosis in melanoma development, can be activated by reactive oxygen species without any known mutation." (PMID 24358134, 2013). "Meanwhile the same compound activated Rac1, a Rho family member of small GTPases in B16 melanoma cells." (PMID 22920897, 2013). "BGP-15 activation of HSP expression in B16-F10 mouse melanoma cells involves the Rac1 signaling cascade in accordance with the previous observation that cholesterol affects the targeting of Rac1 to membranes." (PMID 22174906, 2011). "Mesenchymal melanoma morphology and invasiveness style is controlled by a Rac1 activation pathway, mediated by adaptor protein NEDD9 and DOCK3, acting as a Rac1-GEF." (PMID 20822528, 2010). "In contrast, RAC1-P29S melanoma tumors do not carry any enriched mutational signature vs. WT-counterparts (p = n.s.)." (PMID 39941730, 2025). "Therefore, it is somewhat surprising that FAK inhibition can be highly effective in melanoma cells expressing constitutively activated Rac1, such as A375 Rac1 P29S and VRPP3 cells." (PMID 41109929, 2025). "Since Src kinases function together with FAK, we hypothesized that co-targeting BRAF/MEK and FAK with avutometinib (RAF/MEK clamp) plus defactinib (FAKi) would show activity against Rac1-driven drug-resistant melanoma cells." (PMID 41109929, 2025). "Having demonstrated that the significant translational potential of cotargeting of MAPK and PREX2/RAC1/p110β, we next tested whether the same was true in immunocompetent, autochthonous melanoma GEMMs." (PMID 39636745, 2025). "Notably, DOCK2 is a potent RAC1 activator in cancers, including melanoma and chronic lymphocytic leukemia, and regulates critical processes such as lymphocyte migration, T-cell differentiation, cell-cell adhesion, and bone marrow homing of immune cells." (PMID 41034404, 2025). "Targeting RAC1 activity via genetic disruption of PREX2 can enhance sensitivity to MAPK inhibition in BRAF-V600E–driven melanoma in vivo, although pharmacologic targeting of the RAC1 effector p110β also seems capable of enhancing responses to MAPK inhibition in vitro." (PMID 39636745, 2025).
melanoma (continued). "In summary, our studies indicate that cotargeting of the MAPK and PREX2/RAC1/p110β signaling axes may be an efficacious therapeutic strategy in BRAFV600E-driven melanoma." (PMID 39636745, 2025). "We previously observed that Rac1-Src signaling appears to drive BRAFi/MEKi resistance selectively in less differentiated melanoma cell lines such as A375 and 451Lu, which display downregulated MITF target gene expression and upregulated YAP/TAZ target gene expression." (PMID 41109929, 2025). "Moreover, activation of Rac1 guanine exchange factors (GEFs) also promotes MAPKi-resistance, particularly in undifferentiated melanoma cells." (PMID 41109929, 2025). "Compared to MITFlow melanoma cells, such as A375 and 451Lu, cells with a more differentiated, MITFhi phenotype prior to drug treatment may be less able to utilize Rac1 signaling during drug adaptation." (PMID 41109929, 2025). "Interestingly, RAC1 was activated in human melanoma cells between 8–16 hours after the initiation of treatment with trametinib." (PMID 40909781, 2025). "In addition, 451Lu melanoma cells expressing Rac1 P29S were also somewhat more resistant to ERK inhibition compared to vector control cells." (PMID 41109929, 2025). "Here, we demonstrate that genetic or therapeutic targeting of the PREX2/RAC1/p110β pathway can substantially enhance responses to MAPK targeting in BRAF-mutant melanoma both in vitro and in vivo, presumably through suppression of AKT/mTOR driven cell-cycle progression." (PMID 39636745, 2025). "Additionally, the presence of activated Rac1 appears to create a dependency on focal adhesion kinase (FAK) signaling in undifferentiated melanoma cells." (PMID 41109929, 2025). "Moreover, RAC1-P29S–mutant melanoma cells have been recently shown to be refractory to p110β selective monotherapy, albeit in vitro, even though RAC1 activation directly regulates p110β." (PMID 39636745, 2025). "Furthermore, they suggest an opportunity for RAC1 pathway targeting agents in resistance-breaking combination approaches for BRAF-mutant melanoma." (PMID 39636745, 2025). "In another study, melanoma cells expressing mutant Rac1 showed increased lamellipodium formation." (PMID 38791951, 2024). "Moreover, research indicates that decreasing Rac1 expression can attenuate the migration and invasion of melanoma cells." (PMID 38956424, 2024). "Therefore, we intended to explore the functional role of RAC1 in melanoma cells, A375 and A875 cells." (PMID 37217516, 2023). "This meaningful and interesting discovery of RAC1 influences in immune checkpoints might provide additional therapeutic targets for immune treatment in melanoma." (PMID 37217516, 2023). "Due to the involvement of Rac1 in multiple human cancers, it was inferred that Myo7a could exert tumour-promoting phenotypes by promoting RhoGDI2 expression levels and consequently Rac1 activity in B16 melanoma." (PMID 36835422, 2023). "The Rac1(P29S) mutant was first identified in melanoma samples by two seminal studies." (PMID 37114375, 2023). "Furthermore, it was reported that a melanoma-derived mutant RAC1 (RAC1 P29S) selectively drives the expression of PD-L1, a major immune-evasive molecule." (PMID 37830586, 2023). "In addition, we analysed RAC1 expression in a skin cutaneous melanoma cohort and an acral melanoma cohort in TCGA and cBioPortal databases and found that high expression of RAC1 indicated a worse clinical prognosis of melanoma patients." (PMID 35534866, 2022). "Moreover, our findings suggests that melanomas differ with respect to utilization of RAC1-signaling." (PMID 36271142, 2022). "Researchers have revealed that FMRP may regulate the translation process of RAC1 in Drosophila and mice, but the relationship between the two in melanoma is unknown." (PMID 35534866, 2022). "Lastly, we wondered whether intrinsic or enforced RAC1 signaling regulates melanoma differentiation." (PMID 36271142, 2022).